ILDR2 (immunoglobulin like domain containing receptor 2)
Description:
May be involved in ER stress pathways with effects on lipid homeostasis and insulin secretion. With ILDR1 and LSR, involved in the maintain of the epithelial barrier function through the recruitment of MARVELD2/tricellulin to tricellular tight junctions (By similarity). Also functions as a B7-like protein family member expressed on immune cells and inflamed tissue and with T-cell inhibitory activity. In the inner ear, may regulate alternative pre-mRNA splicing via binding to TRA2A, TRA2B and SRSF1 (By similarity).
Synonyms: C1orf32; dJ782G3.1
Tractability: Antibody: UniProt predicts a signal peptide or a membrane-spanning region; the Human Protein Atlas places it where antibodies can reach. PROTAC: ubiquitination databases record sites on it; its protein half-life has been measured.
Gene: Protein-coding gene on chromosome 1 (166,895,711 to 166,975,540, reverse strand). Ensembl gene ENSG00000143195.
Subcellular location: Endoplasmic reticulum membrane; Cell junction, tight junction; Nucleus
Subcellular location (Human Protein Atlas): Plasma membrane
Gene Ontology:
Biological process: negative regulation of T cell activation; pancreas development; regulation of RNA splicing
Cellular component: endoplasmic reticulum membrane; membrane; nucleus; tight junction; bicellular tight junction
Genetic constraint (gnomAD): Loss-of-function variants: 22 observed, 50.5 expected, observed/expected ratio (o/e) 0.44, 90% interval 0.31 to 0.62. The upper end of that interval is the gene's LOEUF score, 0.62, which puts it in group 2 of 6, group 1 being the genes least tolerant of losing a copy. Missense variants: 786 observed, 761.3 expected, observed/expected ratio (o/e) 1.03, 90% interval 0.97 to 1.1. Synonymous variants: 349 observed, 313.64 expected, observed/expected ratio (o/e) 1.11, 90% interval 1.02 to 1.22.
Homologues: Orthologues: chimpanzee ILDR2 (100% identical), macaque ILDR2 (97% identical), pig ILDR2 (92% identical), rat Ildr2 (90% identical), mouse Ildr2 (88% identical), guinea pig ILDR2 (80% identical), dog ILDR2 (79% identical), tropical clawed frog ildr2 (57% identical), zebrafish ildr2 (37% identical), zebrafish si:zfos-1011f11.2 (14% identical). Paralogues in human: LSR (33% identical), ILDR1 (22% identical).
Diseases named in the same sentence as ILDR2 in open-access papers:
ILDR2 is named in the same sentence as 17 diseases in open-access papers, as found by Europe PMC text mining. Sharing a sentence is not in itself a finding about the gene and the disease. The quoted sentences say what the papers report.
autoimmune disease (5 papers, 2021 to 2025). A disorder resulting from loss of function or tissue destruction of an organ or multiple organs, arising from humoral or cellular immune responses of the individual to their own tissue constituents. "Ildr2 has pivotal roles in immunomodulation and maintenance of peripheral self-tolerance, evincing immunomodulatory activity and the ability to ameliorate autoimmune disease states in various mouse models." (PMID 37325559, 2023). "ILDR2-Fc regulates the function of immunity in the treatment of autoimmune diseases by regulating the stability of the immune internal environment and rebuilding the balance of immune tolerance." (PMID 35595813, 2022). "Collectively, ILDR2 plays a possible shared role in the progress of both cancer and autoimmune diseases." (PMID 34639059, 2021). "Additionally, we found increased expression of immunoglobulin-like domain-containing receptor 2 (Ildr2), a gene involved in immune tolerance and T cell regulation in autoimmune diseases and cancer." (PMID 41008788, 2025). "In an animal model of autoimmune disease, treatment with ILDR2-Fc, which fused the extracellular domain of ILDR2 with the fragment crystallizable (Fc) portion of immunoglobulin G (IgG), was improved by regulating immune homeostasis and inducing antigen-specific immune tolerance." (PMID 33863978, 2021). "This immunomodulatory activity related to ILDR2 and its effect on antigen-specific immunological tolerance has been demonstrated in various autoimmune disease models such as mouse models in rheumatoid arthritis (RA), type I diabetes, and multiple sclerosis (MS)." (PMID 34639059, 2021).
diabetes (5 papers, 2008 to 2021). "Ildr2 was initially identified as a genetic modifier of diabetes susceptibility in B6.DBA Lepob congenic mice, and was associated with decreased β-cell replication rates, reduced β-cell mass, and persistent mild hypoinsulinemic hyperglycemia." (PMID 33863978, 2021). "Ildr2 was initially identified as modifier of diabetes susceptibility, and ongoing work in our lab has confirmed its role in beta cell function, glucose homeostasis, and metabolic partitioning of energy stores." (PMID 29847571, 2018). "Initially identified by positional genetics as a diabetes-susceptibility gene in mice, Ildr2 knockdown via adenovirally-delivered shRNA (ADKD) resulted in gross hepatic steatosis and inflammation within 10 days of infection." (PMID 29847571, 2018).
Hepatic steatosis (3 papers, 2013 to 2022). Steatosis is a term used to denote lipid accumulation within hepatocytes. "We have previously reported that Ildr2 knockdown via adenovirally-delivered shRNA causes hepatic steatosis in mice." (PMID 29847571, 2018). "Ildr2 knockdown mice showed hepatic steatosis, with increased hepatic and circulating TG and CHO in the liver." (PMID 36557314, 2022). "Ildr2 shRNA is 63% homologous to the Dgka gene, and Dgka expression decreased only in mice displaying hepatic steatosis." (PMID 29847571, 2018). "We discuss the development of liver-specific Ildr2 knockout (KO) mice and further characterize them to understand the putative role of Ildr2 in hepatic steatosis." (PMID 29847571, 2018). "Use of appropriate controls enabled us to deconvolute the effects of Ildr2 expression on hepatic steatosis in our various mouse models; however, the confounding effects of using adenovirus as a primary delivery system remain a significant issue." (PMID 29847571, 2018). "In this study we describe several mouse models developed in an effort to replicate the hepatic steatosis phenotype of adenoviral Ildr2 shRNA KD mice." (PMID 29847571, 2018). "Rather, hepatic steatosis observed previously in Ildr2 knockdown mice was likely due to shRNA targeting of Dgka and/or other “off-target” genes." (PMID 29847571, 2018). "Overexpression of the ER stress chaperone BIP (GRP78) in ob/ob mice (as with Ildr2) reverses hepatic steatosis, and hypomorphic expression of UPR modulators Atf6, Ire1α, Chop, and Crebh in mouse models cause hepatic dyslipidemia." (PMID 23826244, 2013). "Overexpression of Ildr2 in ob/ob mice substantially rescued their hepatic steatosis, as Ildr2 over-expressing mice had significantly decreased hepatic TG and TCH and reduced periportal vacuolar deposition." (PMID 23826244, 2013). "We conclude that ILDR2 plays a negligible role in hepatic steatosis." (PMID 29847571, 2018). "Since we showed that adenoviral treatment alone does not cause hepatic steatosis, so we turned our attention to the Ildr2 shRNA." (PMID 29847571, 2018). "We have clearly shown that loss of Ildr2—whether specifically in hepatocytes or in all liver cells—is not sufficient to cause hepatic steatosis." (PMID 29847571, 2018). "Ildr2-mediated effects on lipid homeostasis and ER stress responses could account for both the hepatic steatosis observed in the ADKD animals reported here, and the reduced β-cell mass and accompanying glucose intolerance in the Chr 1 B6.DBA ob/ob congenic animals." (PMID 23826244, 2013). "No liver steatosis or dyslipidemia were seen in Ildr2Adv or Ildr2AAV KO mice despite complete Ildr2 ablation in liver." (PMID 29847571, 2018). "In either case, the major trigger for hepatic steatosis is the Ildr2 shRNA, not Ildr2 ablation per se." (PMID 29847571, 2018). "However, none of these KO models recapitulated the phenotype of hepatic steatosis observed in the adenoviral Ildr2 shRNA KD mice." (PMID 29847571, 2018). "Taken together, these results suggest that Ildr2 ablation in non-parenchymal liver cells could contribute to the steatotic phenotypes of the ADKD mice, and thus explain the lack of hepatic steatosis in the acute and congenital transgenic hepatocyte-specific KO mice." (PMID 29847571, 2018).
hepatoma (2 papers, 2013 to 2017). "In fact, exogenous ILDR2 has been shown to primarily locate in the ER of cultured hepatoma and neuronal cells." (PMID 28785060, 2017). "In hepatoma and neuronal cells, ILDR2 is primarily located in the endoplasmic reticulum membrane." (PMID 23826244, 2013).
Hyperglycemia (2 papers, 2013 to 2021). An increased concentration of glucose in the blood. "Additionally, adenoviral ILDR2 knockdown led to reduced glucose-responsive insulin secretion in MIN6 β-cells, suggesting ILDR2 may be implicated in a new pathway in hypoinsulinemic hyperglycemia." (PMID 33863978, 2021). "The identification of an association between decreased ILDR2 expression in β-cells and decreased insulin secretion may potentially represent a component of a new pathway in hypoinsulinemic hyperglycemia and provide a new mechanism for decreased insulin secretion." (PMID 33863978, 2021). "The association between suppressed ILDR2 expression in β-cells and decreased insulin secretion may be an important component of a new pathway in hypoinsulinemic hyperglycemia, and thus may be a target for diabetic therapeutic modulation for decreased insulin secretion." (PMID 33863978, 2021). "Since neither insulin resistance nor hyperglycemia was present in the ADKD mice (similar in this regard to the phenotype of mice hypomorphic for hepatic Atgl), we investigated other mechanisms relating Ildr2 to hepatic steatosis." (PMID 23826244, 2013).
Hypoinsulinemia (1 paper, 2021). A decreased concentration of insulin in the blood. "In the future, using β-cell specific Ildr2-knockout mice, we will examine how Ildr2 reductions cause decreased β-cell replication rates, decreased β-cell mass, and persistent mild hypoinsulinemia." (PMID 33863978, 2021).
nonsyndromic deafness (1 paper, 2017). An auditory system disease that is associated with permanent hearing loss caused by damage to structures in the inner ear and/or the middle ear, which is not associated with other signs and symptoms. "Consistently, LSR has two homologous genes known as ILDR1 and ILDR2, of which mutations in ILDR1 result in familial nonsyndromic deafness." (PMID 28767685, 2017).
steatosis (1 paper, 2018). Increased lipid within the cytoplasm of cells. "Thus, we were driven to consider that the steatosis had been caused by a consequence of the shRNA antisense construct–primarily unrelated to the decrease in Ildr2 expression." (PMID 29847571, 2018). "Thus, it is possible that KD of candidate gene(s) interacts with Ildr2 hypomorphism to induce steatosis." (PMID 29847571, 2018). "To identify additional gene(s) that might have been knocked down by the Ildr2 shRNA, and thus have contributed to development of steatosis in ADKD mice, we performed RNA sequencing analysis on liver samples from ADKD and AD-lacZ mice (from our previously published ADKD study) and Ildr2Adv KO mice." (PMID 29847571, 2018). "Next, we considered the possibility that loss of Ildr2 in non-parenchymal liver cells may have contributed significantly to the steatosis observed in our original ADKD mice." (PMID 29847571, 2018). "Compensation for the loss of Ildr2 in Ildr2Alb KO mice could theoretically explain the absence of increased steatosis in the Ildr2Alb KO mice." (PMID 29847571, 2018). "Since these mice do not express Ildr2 in the hepatocytes, any steatosis observed would be the result of shRNA targeting of other genes affecting lipid metabolism." (PMID 29847571, 2018). "Despite complete KO of Ildr2, livers of Ildr2AAV KO mice were normal, showing neither steatosis nor any lipid metabolic abnormalities when compared to mice injected with the AAV8-TBG-GFP control construct." (PMID 29847571, 2018). "A reduction in adenoviral activity could also explain the difference in lipid accumulation and severity of steatosis between ADKD mice and Ildr2Alb KO mice infected with Adv-Ildr2 shRNA." (PMID 29847571, 2018). "The absence of steatosis in Ildr2Alb KO mice led us to postulate that the congenital nature of the KO may have triggered gene compensation for the lack of ILDR2 during development." (PMID 29847571, 2018).
cancer (4 papers, 2021 to 2025). A tumor composed of atypical neoplastic, often pleomorphic cells that invade other tissues. "In addition, more research should be done on the role of these ligands and other members of the B7 family, such as B7-H7and ILDR2 (new members of this group), on the drug resistance of cancer cells." (PMID 35684481, 2022). "Therefore, targeting ILDR2 via BAY 1905254 is effective for the immunotherapy of cancer." (PMID 34639059, 2021).
infection (3 papers, 2018 to 2025). The state of being infected such as from the introduction of a foreign agent such as serum, vaccine, antigenic substance or organism. "Another concern is that the amount of active Ildr2 shRNA adenovirus used to infect Ildr2Alb KO mice may have decreased from its activity level at the time of ADKD infection." (PMID 29847571, 2018). "At 48 h infection, GSIS analyses indicated that insulin secretion was reduced in ILDR2-knockdown cells at both high glucose and KCl stimulation levels." (PMID 33863978, 2021).
ILDR2 also shares sentences with these, for which no sentence is quoted: Obesity (2 papers); type 2 diabetes (2); dyslipidemia (1); Glucose intolerance (1); Insulin resistance (1); metabolic disorders (1); rheumatoid arthritis (1).